ITGB3 (integrin subunit beta 3)
Description:
Integrin alpha-V/beta-3 (ITGAV:ITGB3) is a receptor for cytotactin, fibronectin, laminin, matrix metalloproteinase-2, osteopontin, osteomodulin, prothrombin, thrombospondin, vitronectin and von Willebrand factor. Integrin alpha-IIb/beta-3 (ITGA2B:ITGB3) is a receptor for fibronectin, fibrinogen, plasminogen, prothrombin, thrombospondin and vitronectin. Integrins alpha-IIb/beta-3 and alpha-V/beta-3 recognize the sequence R-G-D in a wide array of ligands. Integrin alpha-IIb/beta-3 recognizes the sequence H-H-L-G-G-G-A-K-Q-A-G-D-V in fibrinogen gamma chain (By similarity). Following activation integrin alpha-IIb/beta-3 brings about platelet/platelet interaction through binding of soluble fibrinogen. This step leads to rapid platelet aggregation which physically plugs ruptured endothelial surface. Fibrinogen binding enhances SELP expression in activated platelets (By similarity). ITGAV:ITGB3 binds to fractalkine (CX3CL1) and acts as its coreceptor in CX3CR1-dependent fractalkine signaling. ITGAV:ITGB3 binds to NRG1 (via EGF domain) and this binding is essential for NRG1-ERBB signaling. ITGAV:ITGB3 binds to FGF1 and this binding is essential for FGF1 signaling. ITGAV:ITGB3 binds to FGF2 and this binding is essential for FGF2 signaling. ITGAV:ITGB3 binds to IGF1 and this binding is essential for IGF1 signaling. ITGAV:ITGB3 binds to IGF2 and this binding is essential for IGF2 signaling. ITGAV:ITGB3 binds to IL1B and this binding is essential for IL1B signaling. ITGAV:ITGB3 binds to PLA2G2A via a site (site 2) which is distinct from the classical ligand-binding site (site 1) and this induces integrin conformational changes and enhanced ligand binding to site 1. ITGAV:ITGB3 acts as a receptor for fibrillin-1 (FBN1) and mediates R-G-D-dependent cell adhesion to FBN1. In brain, plays a role in synaptic transmission and plasticity. Involved in the regulation of the serotonin neurotransmission, is required to localize to specific compartments within the synapse the serotonin receptor SLC6A4 and for an appropriate reuptake of serotonin. Controls excitatory synaptic strength by regulating GRIA2-containing AMPAR endocytosis, which affects AMPAR abundance and composition (By similarity). ITGAV:ITGB3 act as a receptor for CD40LG. ITGAV:ITGB3 acts as a receptor for IBSP and promotes cell adhesion and migration to IBSP. Integrin ITGA2B:ITGB3 is also the receptor of the erythrocyte-specific ICAM4 ligand involved in heterotypic cell-cell adhesion between erythrocytes and activated platelets. (Microbial infection) Integrin ITGAV:ITGB3 acts as a receptor for Herpes virus 8/HHV-8. (Microbial infection) Integrin ITGAV:ITGB3 acts as a receptor for Coxsackievirus A9. (Microbial infection) Acts as a receptor for Hantaan virus. (Microbial infection) Integrin ITGAV:ITGB3 acts as a receptor for Cytomegalovirus/HHV-5. (Microbial infection) Integrin ITGA5:ITGB3 acts as a receptor for Human metapneumovirus. (Microbial infection) Integrin ITGAV:ITGB3 acts aP05556s a receptor for Human parechovirus 1. (Microbial infection) Integrin ITGAV:ITGB3 acts as a receptor for West nile virus. (Microbial infection) In case of HIV-1 infection, the interaction with extracellular viral Tat protein seems to enhance angiogenesis in Kaposi's sarcoma lesions.
Synonyms: GPIIIa; CD61; GP3A; BDPLT16; BDPLT2; BDPLT24; FMAIT1; GT; GT2
Tractability: Small molecule: an approved drug acts on it; a structure with a bound ligand is known; a high-quality ligand is known; it belongs to a druggable protein family. Antibody: an approved drug acts on it; UniProt places it where antibodies can reach, with high confidence; its Gene Ontology location is reachable by antibodies, with high confidence; UniProt predicts a signal peptide or a membrane-spanning region; the Human Protein Atlas places it where antibodies can reach. PROTAC: ubiquitination databases record sites on it; a small molecule that binds it is known. Other modalities: an approved drug acts on it.
Target class: Membrane receptor
Chemical probes: PD080686, PD081484, PD082403, PD084558, PD084834, PD085170
Gene: Protein-coding gene on chromosome 17 (47,253,827 to 47,313,743, forward strand). Ensembl gene ENSG00000259207.
Subcellular location: Cell membrane; Cell projection, lamellipodium membrane; Cell junction, focal adhesion; Postsynaptic cell membrane; Synapse
Subcellular location (Human Protein Atlas): Plasma membrane; Nucleoplasm
Pathways (Reactome):
Disease: Paradoxical activation of RAF signaling by kinase inactive BRAF; Signaling by BRAF and RAF1 fusions; Signaling by RAF1 mutants; Signaling by high-kinase activity BRAF mutants; Signaling by moderate kinase activity BRAF mutants; Signaling downstream of RAS mutants
Signal Transduction: GRB2:SOS provides linkage to MAPK signaling for Integrins; Integrin signaling; MAP2K and MAPK activation; TGF-beta receptor signaling activates SMADs; VEGFA-VEGFR2 Pathway; p130Cas linkage to MAPK signaling for integrins
Extracellular matrix organization: ECM proteoglycans; Elastic fibre formation; Integrin cell surface interactions; Molecules associated with elastic fibres; Syndecan interactions
Hemostasis: Fibrin formation; PECAM1 interactions; Platelet degranulation
Cellular responses to stimuli: Mechanical load activates signaling by PIEZO1 and integrins in osteocytes; Turbulent (oscillatory, disturbed) flow shear stress activates signaling by PIEZO1 and integrins in endothelial cells
Developmental Biology: Signal transduction by L1
Gene Ontology:
Molecular function: C-X3-C chemokine binding; cell adhesion molecule binding; cell adhesion receptor activity; enzyme binding; extracellular matrix binding; fibroblast growth factor binding; fibronectin binding; identical protein binding; insulin-like growth factor I binding; integrin binding; neuregulin binding; protease binding; protein binding; protein disulfide isomerase activity; vascular endothelial growth factor receptor 2 binding; coreceptor activity; fibrinogen binding; platelet-derived growth factor receptor binding; protein kinase C binding
Biological process: apolipoprotein A-I-mediated signaling pathway; apoptotic cell clearance; cell adhesion mediated by integrin; cell-cell adhesion mediated by integrin; cell-matrix adhesion; cell-substrate adhesion; heterotypic cell-cell adhesion; integrin-mediated signaling pathway; mesodermal cell differentiation; negative chemotaxis; negative regulation of lipid storage; negative regulation of lipid transport; negative regulation of lipoprotein metabolic process; negative regulation of low-density lipoprotein particle clearance; negative regulation of macrophage derived foam cell differentiation; platelet activation; platelet aggregation; positive regulation of endothelial cell migration; positive regulation of endothelial cell proliferation; positive regulation of vascular endothelial growth factor signaling pathway; regulation of postsynaptic neurotransmitter receptor internalization; smooth muscle cell migration; substrate adhesion-dependent cell spreading; symbiont entry into host cell; angiogenesis involved in wound healing; and 41 more
Cellular component: alphav-beta3 integrin-HMGB1 complex; alphav-beta3 integrin-IGF-1-IGF1R complex; alphav-beta3 integrin-PKCalpha complex; cell surface; cell-cell junction; extracellular exosome; filopodium membrane; focal adhesion; glutamatergic synapse; integrin alphaIIb-beta3 complex; integrin alphav-beta3 complex; integrin complex; lamellipodium membrane; melanosome; microvillus membrane; nucleus; plasma membrane; protein-containing complex; receptor complex; ruffle membrane; alphav-beta3 integrin-vitronectin complex; platelet alpha granule membrane; synapse; apical plasma membrane; external side of plasma membrane; and 5 more
Genetic constraint (gnomAD): Loss-of-function variants: 46 observed, 85.92 expected, observed/expected ratio (o/e) 0.54, 90% interval 0.42 to 0.69. The upper end of that interval is the gene's LOEUF score, 0.69, which puts it in group 2 of 6, group 1 being the genes least tolerant of losing a copy. Missense variants: 857 observed, 1,049.9 expected, observed/expected ratio (o/e) 0.82, 90% interval 0.77 to 0.86. Synonymous variants: 361 observed, 401.96 expected, observed/expected ratio (o/e) 0.9, 90% interval 0.82 to 0.98.
Gene-disease validity (ClinGen):
ClinGen rates the evidence that ITGB3 causes each of these diseases.
Glanzmann thrombasthenia (autosomal recessive): Definitive.
platelet-type bleeding disorder 16 (autosomal dominant): Definitive.
Homologues: Orthologues: chimpanzee ITGB3 (99% identical), dog ITGB3 (95% identical), macaque ITGB3 (93% identical), pig ITGB3 (91% identical), rabbit ITGB3 (91% identical), mouse Itgb3 (91% identical), rat Itgb3 (90% identical), guinea pig ITGB3 (87% identical), tropical clawed frog itgb3 (74% identical), zebrafish itgb3b (69% identical), zebrafish itgb3a (62% identical). Paralogues in human: ITGB5 (55% identical), ITGB6 (49% identical), ITGB1 (43% identical), ITGB7 (38% identical), ITGB2 (38% identical), ITGB4 (37% identical), ITGB8 (33% identical), ITGBL1 (17% identical).
Diseases named in the same sentence as ITGB3 in open-access papers:
ITGB3 is named in the same sentence as 238 diseases in open-access papers, as found by Europe PMC text mining. Sharing a sentence is not in itself a finding about the gene and the disease. The quoted sentences say what the papers report.
breast cancer (70 papers, 2005 to 2025). A primary or metastatic malignant neoplasm involving the breast. "Having established that ITGB3 is fundamental for EV uptake in breast cancer cell lines, we explored the underlying mechanisms." (PMID 32848136, 2020). "ITGB3 expression has been linked with tumor aggression and metastasis to the bone and brain in breast cancer by a mechanism involving FAK and Akt signaling." (PMID 29728077, 2018). "ITGB3 is expressed in a subpopulation of breast cancer stem cells and is associated with poor outcome." (PMID 29383126, 2017). "Indeed, ITGB1 and ITGB3 have been reported to play an important role in HER-2-induced mammary tumor growth and metastasis to the lungs, and this is associated with the promotion of signaling through the insulin receptor-AKT-mTORC1 pathway." (PMID 37175499, 2023). "Previous studies showed that ITGB3 expression is related to tumor invasion and metastasis in breast cancer through mechanisms involving FAK and Akt signal transduction." (PMID 39754146, 2025). "This study focuses on examining the relationship between the expression of these specific genes and ITGB3 heterogeneity in Trastuzumab-resistant HER2-positive breast cancer cells." (PMID 39857240, 2024). "The regulatory role of ITGB3 in tumor stemness has been identified in breast cancer, pancreatic cancer and melanoma." (PMID 39239559, 2024). "This study provides valuable insights into the role of ITGB3 in Trastuzumab resistance in HER2-positive breast cancer, but several limitations should be considered." (PMID 39857240, 2024). "In our previous study ITGB3 expression was found to significantly increase in HER2-positive breast cancer cell lines among eight RGD-binding integrins, promoting stemness through Notch signaling." (PMID 39201327, 2024). "The ITGB3 protein, known as the integrin beta chain beta 3, was identified as an epithelial-to-mesenchymal transition biomarker in colorectal cancer, prostate cancer, and breast cancer." (PMID 38183097, 2024). "In this study, ITGB3 was identified as a critical factor contributing to Trastuzumab resistance in HER2-positive breast cancer." (PMID 39857240, 2024). "Trastuzumab-resistant HER2-positive HCC1954 and SKBR3 breast cancer cell lines were generated and analysed for ITGB3 expression heterogeneity." (PMID 39857240, 2024). "ITGB3 likely contributes to skeletal metastasis through its modulation of gene expression, a common complication in the progression of breast cancer." (PMID 39000458, 2024). "Using resistant breast cancer cell lines, researchers found that ITGB3 expression varied widely and was correlated with increased migration and signaling activity." (PMID 39857240, 2024). "In this study, Trastuzumab-resistant cell lines were generated from HCC1954 and SKBR3, two HER2-positive breast cancer cell lines, and the heterogeneity in ITGB3 expression among these resistant clones was examined." (PMID 39857240, 2024). "The bone marrow also expresses high levels of FN1, and this environment appears to induce ITGB3 upregulation in metastasized breast cancer cells." (PMID 39707454, 2024). "Breast cancer cells co-labeled with CD49f+/CD61+ (ITGB3) exhibit enhanced tumor sphere-forming ability, tumorigenicity, and resistance to chemotherapy drugs." (PMID 39239559, 2024). "A study identified a population of cancer stem cells (CSCs) in a mouse model of breast cancer (MMTV-WT-1) using the luminal epithelial progenitor marker ITGB3 (CD61)." (PMID 39239559, 2024). "We previously reported that the ectopic over-expression of NRP-1 in the HER-2+ breast cancer cell line BT-474 was correlated with an upregulation of the TN-C/Integrinβ3/ITGB3) axis." (PMID 37175499, 2023). "Studies have also demonstrated that interactions between CAFs and breast cancer cells, which are mediated by IL-32 and integrin β3 (ITGB3), play a crucial role in CAF-induced cancer metastasis." (PMID 37217855, 2023).
breast cancer (continued). "ITGB3 also has a central role in intracellular communication via extracellular vesicles, proposed to be critical for cancer metastasis in breast cancer." (PMID 37760946, 2023). "The specific binding of CAF-derived IL-32 to ITGB3 activates the p38 MAPK cascade signaling pathway in breast cancer cells." (PMID 37217855, 2023). "Research shows that the expression of ITGB3 in breast cancer tissue and serum is increased, and silencing ITGB3 can inhibit the metastasis of breast cancer breast epithelial cells." (PMID 37760946, 2023). "Incoherence to breast cancer restricts the cell proliferation, migration, and invasion of gastric cancer and induces apoptosis by targeting ITGB3, Rac1, and Sp1 mRNAs." (PMID 35511336, 2022). "ITGB3 has been reported as a promoter in various carcinomas including breast cancer, hepatocellular carcinoma, and gastric cancer." (PMID 34635968, 2022). "In our study, the NPTN expression was persistently down-regulated in MDA-MB-231 breast cancer cells upon ITGB3 knockdown." (PMID 33083904, 2021). "Integrin β3 (ITGB3) is probably related to skeletal metastasis, which is the most frequent complication in breast cancer progression." (PMID 33083904, 2021). "Based on this pathophysiology, integrin β3 (ITGB3) emerged as a potential target for therapy of breast cancer skeletal metastasis." (PMID 33083904, 2021). "In summary, the conditional inhibition of ITGB3 expression in breast cancer cells is related to anti-proliferative and anti-migratory effects in these cells as well as to decreased amounts of this protein in exosomes shed from these cells." (PMID 33083904, 2021). "The conditional miRNA-mediated ITGB3 knockdown led to a mild but significant inhibition of proliferation and a pronounced reduction in migration of the breast cancer cell clones in vitro." (PMID 33083904, 2021). "Targeting of ITGB3 mRNA by siRNA significantly inhibited the migration of breast cancer cells in vitro." (PMID 33083904, 2021). "Here we aimed to create a model for monitoring the anti-ITGB3 effects in breast cancer cells, starting from a freely chosen onset, and continued for a defined period in vitro or in vivo." (PMID 33083904, 2021). "We found that ITGB3 knockdown rendered breast cancer cells insensitive to secreted factors in their environment, reducing their clonal growth capacity." (PMID 32848136, 2020). "The integrin ITGB3 has been described to play an essential role in breast cancer metastasis, but the precise mechanisms remain undefined." (PMID 32848136, 2020). "Our study in the BT-474 breast cancer model provides further insight into this pathway by highlighting the role of NRP-1 in triggering ITGB3/FAK/Akt-473 in a TNC-dependent pathway to trigger cell migration." (PMID 29728077, 2018). "Considering the important role of ITGB3 in tumourigenesis, we further studied ITGB3 in breast cancer cells under hypoxic conditions." (PMID 29383126, 2017). "Increased ITGB3 facilitates the migratory and invasive capabilities of breast cancer cells through induction of Snail and epithelial-mesenchymal transition (EMT) via the TGF-β pathway, an effect particularly evident under hypoxic conditions." (PMID 29383126, 2017). "There are few studies of the function of miR-320a, including its inhibition of ARDP-19/ERRr in breast cancer and targeting ITGB3 in bladder carcinoma." (PMID 27086911, 2016). "ITGB3 has emerged as a promising therapeutic target for breast cancer skeletal metastasis." (PMID 39000458, 2024). "The integrin pair ITGAV:ITGB3 is expressed in breast cancer and can mediate metastasis to the bone." (PMID 39707454, 2024). "Furthermore, the ITGAV:ITGB3 integrin pair plays a role in cell survival following radiation therapy in both prostate cancer and breast cancer." (PMID 39707454, 2024).